TRAV8-2 (T cell receptor alpha variable 8-2)
Description:
V region of the variable domain of T cell receptor (TR) alpha chain that participates in the antigen recognition. Alpha-beta T cell receptors are antigen specific receptors which are essential to the immune response and are present on the cell surface of T lymphocytes. Recognize peptide-major histocompatibility (MH) (pMH) complexes that are displayed by antigen presenting cells (APC), a prerequisite for efficient T cell adaptive immunity against pathogens. Binding of alpha-beta TR to pMH complex initiates TR-CD3 clustering on the cell surface and intracellular activation of LCK that phosphorylates the ITAM motifs of CD3G, CD3D, CD3E and CD247 enabling the recruitment of ZAP70. In turn ZAP70 phosphorylates LAT, which recruits numerous signaling molecules to form the LAT signalosome. The LAT signalosome propagates signal branching to three major signaling pathways, the calcium, the mitogen-activated protein kinase (MAPK) kinase and the nuclear factor NF-kappa-B (NF-kB) pathways, leading to the mobilization of transcription factors that are critical for gene expression and essential for T cell growth and differentiation. The T cell repertoire is generated in the thymus, by V-(D)-J rearrangement. This repertoire is then shaped by intrathymic selection events to generate a peripheral T cell pool of self-MH restricted, non-autoaggressive T cells. Post-thymic interaction of alpha-beta TR with the pMH complexes shapes TR structural and functional avidity.
Synonyms: TCRAV1S5; TCRAV8S2; TRAV82
Gene: T-cell receptor variable (V) gene on chromosome 14 (21,846,537 to 21,847,221, forward strand). Ensembl gene ENSG00000211786.
Subcellular location: Cell membrane
Gene Ontology:
Biological process: adaptive immune response
Cellular component: immunoglobulin complex; plasma membrane
Homologues: Paralogues in human: TRAV8-4 (92% identical), TRAV8-6 (77% identical), TRAV8-3 (65% identical), TRAV8-7 (64% identical), TRAV8-1 (60% identical), TRAV3 (58% identical), TRAV16 (52% identical).